GPR119 (G protein-coupled receptor 119)
Description:
Receptor for the endogenous fatty-acid ethanolamide oleoylethanolamide (OEA) and lysophosphatidylcholine (LPC). Functions as a glucose-dependent insulinotropic receptor. The activity of this receptor is mediated by G proteins which activate adenylate cyclase. Seems to act through a G(s) mediated pathway.
Synonyms: hGPCR2; GPCR2
Tractability: Small molecule: a drug acting on it is in phase 2 or 3 trials; a structure with a bound ligand is known; a high-quality ligand is known; it belongs to a druggable protein family. Antibody: UniProt places it where antibodies can reach, with medium confidence; UniProt predicts a signal peptide or a membrane-spanning region; its Gene Ontology location is reachable by antibodies, with medium confidence. PROTAC: ubiquitination databases record sites on it; a small molecule that binds it is known.
Target class: Small molecule receptor (family A GPCR); Lipid-like ligand receptor (family A GPCR); Membrane receptor; Family A G protein-coupled receptor
Chemical probes: CHEMBL2086690
Gene: Protein-coding gene on chromosome X (130,379,449 to 130,385,674, reverse strand). Ensembl gene ENSG00000147262.
Subcellular location: Cell membrane
Pathways (Reactome):
Metabolism of proteins: Synthesis, secretion, and inactivation of Glucagon-like Peptide-1 (GLP-1); Synthesis, secretion, and inactivation of Glucose-dependent Insulinotropic Polypeptide (GIP)
Gene Ontology:
Molecular function: protein binding; G protein-coupled receptor activity; phosphatidylcholine binding
Biological process: adenylate cyclase-activating G protein-coupled receptor signaling pathway; G protein-coupled receptor signaling pathway
Cellular component: receptor complex; cytoplasm; plasma membrane; membrane
Homologues: Orthologues: chimpanzee GPR119 (99% identical), macaque GPR119 (96% identical), rabbit GPR119 (84% identical), dog GPR119 (84% identical), pig GPR119 (83% identical), mouse Gpr119 (82% identical), guinea pig GPR119 (77% identical), rat Gpr119 (74% identical), tropical clawed frog gpr119 (32% identical). Paralogues in human: GPR6 (22% identical), S1PR5 (21% identical), CNR1 (21% identical), S1PR1 (21% identical), MC3R (20% identical), MC5R (20% identical), S1PR3 (20% identical), S1PR2 (20% identical), GPR3 (19% identical), LPAR2 (19% identical), CNR2 (19% identical), LPAR1 (19% identical), and 6 more.
Diseases named in the same sentence as GPR119 in open-access papers:
GPR119 is named in the same sentence as 37 diseases in open-access papers, as found by Europe PMC text mining. Sharing a sentence is not in itself a finding about the gene and the disease. The quoted sentences say what the papers report.
diabetes (24 papers, 2010 to 2025). "Mice model studies indicated that N-palmitoylserinol which activates GPR119 regulating glucose homeostasis is associated with obesity and diabetes." (PMID 38029089, 2023). "The new GPR119 agonist ZB-16 (1 mg/kg) decreases the blood glucose levels under fasting conditions in animals with the experimental type 2 diabetes mellitus caused by streptozotocin and nicotinamide." (PMID 28736546, 2017). "At the same time, GPR119 activation also increases glucagon secretion, which may reduce the risk of medically induced hypoglycemia in patients with diabetes undergoing intensive insulin therapy." (PMID 37686185, 2023). "Thus, the new GPR119 agonist ZB-16 demonstrated the mild hypoglycemic activity on glucose-loaded animals with the experimental type 2 diabetes mellitus caused by streptozotocin and nicotinamide administration." (PMID 28736546, 2017). "Multiple-low-dose STZ-induced diabetes was associated with diminished insulin-positive beta cells (p < 0.001), augmented glucagon-positive alpha cells (p < 0.001) and decreased GPR119 expression (p < 0.001)." (PMID 27677765, 2016). "The rhodopsin-like receptor GPR119 plays a crucial role in glucose homeostasis and is an emerging target for the treatment of type 2 diabetes mellitus." (PMID 38288442, 2024). "Such insights are invaluable for advancing our understanding of GPCR activation and its implications for drug development targeting GPR119 in the context of type 2 diabetes mellitus." (PMID 38288442, 2024). "GPR119 has already been pharmacologically targeted for obesity and diabetes because it stimulates insulin secretion by directly acting on pancreatic beta cells or through incretin secretion by gut enteroendocrine cells." (PMID 36462626, 2023). "Since GPR119 has the potential to modulate metabolic homeostasis in obesity and diabetes, it has attracted interest as a therapeutic target." (PMID 36462626, 2023). "GPR119 has been a potential therapeutic target for diabetes mellitus type 2 for many years, but its role in metabolic dysfunction associated fatty liver disease deserves further attention." (PMID 34233623, 2021). "Because GPR119 has significant advantages in blood glucose regulation, it has been a drug target to treat type 2 diabetes mellitus with many excellent results." (PMID 34233623, 2021). "Since the discovery of GPR119 as a receptor for OEA, development of GPR119 agonists as potential pharmacotherapies for diabetes and obesity has been intensively conducted." (PMID 33494185, 2021). "Several novel fatty acid receptors, including GPR55 and GPR119, have shown promise as emerging targets of diabetes therapies." (PMID 27677765, 2016). "Following the de-orphanization of GPR119, small molecules targeting this receptor were developed as potential new treatments for diabetes that would increase secretion from intestinal L-cells." (PMID 26144594, 2016). "The bioactive lipid 5-HEPE is known to be a potent agonist of GPR119 and enhances glucose-dependent insulin secretion, suggesting the molecule as a possible biomarker candidate for diabetes." (PMID 24632803, 2014). "G-protein coupled receptor 119 (GPR119) has emerged as a promising new target for the treatment of type 2 diabetes mellitus." (PMID 24386644, 2013). "As GPR119 protein has been found in both intestinal and islets endocrine cell, this receptor is an attractive target in diabetes therapy." (PMID 23781322, 2013). "In this study, we examined the efficacy of combining a GPR119 agonist (PSN632408) with a DPP-IV inhibitor (sitagliptin) in C57BL/6 mice with STZ-induced diabetes." (PMID 23382843, 2013). "Further, GPR119 mRNA levels were elevated in islets of obese hyperglycemic db/db mice compared with those in control islets, implying a possible involvement of GPR119 in the development of diabetes and obesity." (PMID 33494185, 2021). "GPR119 is a promising target for discovery of anti-type 2 diabetes mellitus agents." (PMID 31656107, 2020).
diabetes (continued). "In conclusion, long-term administration of GPR55 agonist Abn-CBD and GPR119 agonist AS-1269574 improved glycaemic control in a multiple-low-dose STZ-induced mouse model of diabetes, resulting in decreased plasma glucose and glucagon and improved plasma insulin, GLP-1 and lipid profiles." (PMID 27677765, 2016). "Therefore, GPR119 activators may qualify as therapeutic agents to increase human β-cell mass in patients with diabetes." (PMID 27413754, 2016). "Establishing the full repertoire of Gpr119-activated intestinal mechanisms that enhance not only GLP-1 but also PYY-mediated responses with consequent antihyperglycemic effects now provides an optimal platform for a high-affinity Gpr119 agonist to treat diabetes and obesity." (PMID 20519124, 2010). "With regard to diabetes, LPC 18:1 has been shown to be a novel ligand of GPR119, regulating pancreatic insulin secretion." (PMID 32093149, 2020). "We have also identified that several well-characterised GPCRs (CASR, GPRC5B, GPR119, F2RL1), which are either current drug targets or under evaluation as potential diabetes therapeutic targets, are highly expressed in both human and mouse islets." (PMID 28422162, 2017). "We conducted these diabetes studies because GSK263, a potent and selective GPR119 agonist, altered plasma glucose and gut peptide profiles in rodents and healthy subjects (GlaxoSmithKline, unpublished data)." (PMID 24699248, 2014). "In various animal models of obesity and type 2 diabetes, orally available, potent, selective, synthetic GPR119 agonists lowered blood glucose without hypoglycemia, slowed diabetes progression, and reduced food intake and body weight." (PMID 33494185, 2021). "The purpose of this work was to assess the influence of novel GPR119 agonist ZB-16 on the glucose utilization, insulin, and glucagon-like peptide-1 (GLP-1) secretion and the morphology of pancreas in rats with streptozotocin–nicotinamide-induced diabetes." (PMID 28736546, 2017). "Our results demonstrate that combining a GPR119 agonist with a DPP-IV inhibitor may offer a novel therapeutic strategy for stimulating β-cell regeneration and reversing diabetes." (PMID 23382843, 2013). "In addition, it will be interesting to further investigate the effect of combining a GPR119 agonist with a DPP-IV inhibitor on reversing autoimmune diabetes in NOD mice, because DPP-IV inihbitors alone can reverse new-onset diabetes in some NOD mice." (PMID 23382843, 2013). "Since a number of specific receptors (GPR40, GPR41, GPR43, GPR119, and GPR120) expressed on the enteroendocrine L- and K-cells were discovered, there has been an increasing interest in making new effective drugs to treat type 2 diabetes mellitus and metabolic syndrome." (PMID 28736546, 2017).
Obesity (20 papers, 2010 to 2025). Accumulation of substantial excess body fat. "Further research is needed in a variety of cell types and organs to elucidate the pathophysiological role of GPR119 in type 2 diabetes and obesity." (PMID 33494185, 2021). "In normal-weight and healthy patients, it was observed that gut GPR119 expression rapidly increased following acute fat exposure, thus suggesting a potential involvement of GPR119 in type 2 diabetes, metabolic disorders, and obesity." (PMID 32150935, 2020). "From this effort, GPR119 emerged as a promising therapeutic target for the development of orally active, non-peptide, small-molecule agonists to treat type 2 diabetes and obesity." (PMID 33424537, 2020). "In normal-weight and healthy patients it was observed that gut GPR119 expression rapidly increased following acute fat exposure, thus suggesting a potential involvement of GPR119 in type 2 dyabetes, metabolic disorder, and obesity." (PMID 30021985, 2018). "In this study, obesity induced T2DM mice that received chronic administration of our novel GPR119 agonist, HD0471953, showed improved insulin sensitivity and glycemic control without severe hypoglycemia." (PMID 24386644, 2013). "G protein receptor 119 (GPR119) suppresses appetite and may find an application in the treatment of type 2 diabetes and obesity." (PMID 41226575, 2025). "GPR119 agonists might have stimulated PP secretion and induced satiety in patients with type 2 diabetes and obesity." (PMID 33494185, 2021). "The existence of GPR119 in both enteroendocrine cells and also pancreatic β cells encourages the development of novel efficient therapeutics for metabolic disorders including obesity and T2DM." (PMID 26788106, 2015). "Since the GPR119 agonists are able to regulate both food intake and glucose homeostasis, they have a possibility of serving as efficient therapeutics for metabolic disorders such as obesity and T2DM." (PMID 26788106, 2015). "We specifically chose GPR119, GPR84, GPR40, and TGR5 to use as a combined stimulus since these receptors were up-regulated in obesity and RYGB, and as GPR119 and GPR40 have been shown to exhibit synergistic effects on GLP-1 secretion." (PMID 30336615, 2018). "Since G-protein-coupled receptor 119 (GPR119) was introduced as a target for treating T2DM and obesity, 1500 herbal extracts have been screened for GPR119 activation; imperatorin was evaluated as one of the most promising extracts." (PMID 29084156, 2017). "Recently, GPR119 has become a research hotspot: it plays an important role in maintenance of glycemic control; it has been considered as a novel therapeutic target of treating dyslipidemia and NASH; and it has emerged as a drug target for T2DM and obesity." (PMID 37032867, 2023). "In GPR119‐deficient NAFPD mice, terazosin failed to induce the beneficial effects observed in regular NAFPD mice, including improvements in obesity, hyperglycemia, and insulin sensitivity, as well as the increase of β‐cell functional gene expression in the pancreas." (PMID 39413003, 2025). "Therefore, strategies aimed at enhancing the activation of GPR119, such as modulation of microbiota composition to increase OEA production or inhibition of OEA degradation, may help to induce meal satiety in obesity and other eating disorders." (PMID 36462626, 2023). "On the other hand, plasma GIP levels, another response associated with GPR119 activation, were not elevated in Mgll−/− mice following a HFD, as they were in WT mice, in agreement with previous findings of a negative role of this peptide in obesity and/or insulin resistance." (PMID 33348740, 2020). "In this study, terazosin demonstrated beneficial effects on hyperglycemia, obesity, and NAFPD by activating GPR119 rather than acting as a GLP‐1R or analog." (PMID 39413003, 2025). "Increased hepatic expression of Gpr119 and Cd68, but not Cnr1 was also detected in mice with CL-HFS-induced NASH and human patients with obesity and NASH." (PMID 36646715, 2023).
type 2 diabetes (18 papers, 2013 to 2025). "As a result, GPR119 it has become an emerging target for treatment of type 2 diabetes, and its agonist is expected to be a new type of hypoglycemic for treatment of type 2 diabetes." (PMID 38288442, 2024). "GPR119 has emerged as a promising target for type 2 diabetes, with its agonists holding potential as new hypoglycemic agent." (PMID 38288442, 2024). "Although GPR119 is a promising target for type II diabetes and fatty liver diseases, a role of GPR119 in cancer has not been studied." (PMID 30497501, 2018). "GPR119 agonists have been highlighted as ideal therapeutic agents for type 2 diabetes because they increase GLP-1 secretion and can be orally administered." (PMID 27391814, 2016). "We therefore investigated the pharmacology of GSK1292263 (GSK263), a selective GPR119 agonist, in two randomized, placebo-controlled studies that enrolled subjects with type 2 diabetes." (PMID 24699248, 2014). "Its restricted tissue distribution, relative selectivity in enhancing GLP-1 release, and tolerability of its agonists have made GPR119 an attractive therapeutic target for developing orally bioavailable agonists for type 2 diabetes treatment, and potentially for other related disorders." (PMID 33424537, 2020). "Although subsequent trials have not yet demonstrated that metabolic improvements can be brought about by the use of GPR119 agonists in humans with type 2 diabetes, there is still a high level of academic and commercial interest in GPR119 as a potential drug target." (PMID 26144594, 2016). "Therefore, the development of GPR119 agonists is a potential treatment for type 2 diabetes." (PMID 27391814, 2016). "However, clinical studies are needed to determine whether GLP-1 receptor or GPR119 agonists decrease hyperglycemia more effectively than other treatments in patients with type 2 diabetes on simvastatin therapy." (PMID 26561346, 2015). "As the effects of GPR119 activation on islet α-cells are still unknown, glucagon release was also investigated in view of the importance of glucagon for glycemic dysregulation and reduction of glucagon in therapy of type 2 diabetes." (PMID 23781322, 2013). "The activation of GPR119 promotes glucose-stimulated insulin secretion and GLP-1 release, thus GPR119 is considered to be a potential therapeutic target for the treatment of type 2 diabetes." (PMID 27391814, 2016). "Mostly expressed either on intestinal L- and K-cells or pancreatic β-cells, GPR119 had been validated as a potential target for novel pharmacological agents which could become a prominent medicine against type 2 diabetes mellitus (T2D), obesity and metabolic syndrome." (PMID 30283402, 2018). "In conclusion, our data indicate that GPR119 agonism with GSK263 causes substantial changes in circulating total PYY levels, but it did not improve glycemic control in subjects with type 2 diabetes when dosed alone or with metformin or sitagliptin." (PMID 24699248, 2014). "However, despite good evidence of efficacy in animal models, GPR119 agonists did not have metabolic benefits in humans with type 2 diabetes." (PMID 26661410, 2016).
Hyperglycemia (6 papers, 2014 to 2025). An increased concentration of glucose in the blood. "The GPR119/incretin axis may have unique advantages for attenuating hyperglycemia." (PMID 34233623, 2021). "G protein-coupled receptor 119 (GPR119) agonists induce glucagon secretion during hypoglycemia but not hyperglycemia in diabetic mice." (PMID 32774668, 2020). "Previous non-clinical studies and investigations performed in healthy volunteers has established that GPR119 are able to increase the level of circulating incretins including GLP-1, GIP, and tyrosine-tyrosine peptide (PYY), reducing the hyperglycemia after oral glucose load." (PMID 30283402, 2018). "The GPR119 agonists MBX-2982 and PSN821 reduce fasting and post-prandial glucose levels in healthy subjects with fasting hyperglycemia or impaired glucose tolerance and in subjects with T2D, but these drugs may have off-target effects on gastric emptying." (PMID 24699248, 2014). "It is worth noting that GPR119 expression within murine B cells may not be important for the response to hyperglycemia or the direct insulin secretion response to GRP119 agonists in isolated mouse pancreatic islets and GPR119 β-cell-deficient mice." (PMID 34233623, 2021).
Hypoglycemia (6 papers, 2013 to 2023). A decreased concentration of glucose in the blood. "We suggest that this glucose-dependent L-cell response to a gut-restricted GPR119 stimulus has potential therapeutic advantage in modulating insulinotropic signaling with reduced risk of hypoglycemia." (PMID 29471473, 2018). "We propose that this glucose-dependent L-cell response to a gut-restricted GPR119 stimulus has therapeutic potential, either alone or in combination with peptide-stabilizing drugs, in modulating insulinotropic signaling with reduced risk of hypoglycemia." (PMID 29471473, 2018). "Recently, GPR119 activation in pancreatic α-cells was shown to increase glucagon secretion during insulin-induced hypoglycemia." (PMID 33494185, 2021). "Moreover, several GPR119 agonists have been reported to enhance glucagon secretion during hypoglycemia in ex vivo and in vivo experiments." (PMID 36462626, 2023). "Additionally, the glucose dependence of GPR119-triggered incretin release reduces the possibility of hypoglycemia." (PMID 29471473, 2018).